PNPLA3 (patatin like domain 3, 1-acylglycerol-3-phosphate O-acyltransferase )
Diseases named in the same sentence as PNPLA3 in open-access papers (continued):
Sharing a sentence is not in itself a finding about the gene and the disease.
Hepatic steatosis (continued). "Major genetic determinants of hepatic steatosis in the population include PNPLA3 I148M, TM6SF2 E167K and GCKR P446L." (PMID 30355853, 2018). "We analyzed PNPLA3 rs738409 (C/G), MTP493 rs1800591 (G/T), and TM6SF2 rs58542926 (C/T), which are known to be associated with liver steatosis/nonalcoholic steatohepatitis and/or lipid metabolism." (PMID 30576386, 2018). "To determine how the alteration in hepatic lipid composition is related to hepatic steatosis, we analyzed the composition and flux of hepatic FAs in WT, Pnpla3−/− (KO), SA-ki, and IM-ki mice fed a HSD to promote de novo lipogenesis." (PMID 29555681, 2018). "Studies by Hobbs and colleagues previously demonstrated that high expression levels of the mutant PNPLA3 protein are required for the development of hepatic steatosis in mice." (PMID 28244871, 2017). "On the contrary, overexpression of PNPLA3-I148M in mice leads to liver steatosis with elevated lipogenesis and impaired TAG hydrolysis." (PMID 27757845, 2017). "In contrast to their role in hepatic steatosis, CC and TC genotypes of PNPLA3 rs1010023 were correlated to significant improvement of homeostasis model assessment index (HOMA-IR) as compared to TT genotype in the CHB+HS group." (PMID 28695131, 2017). "Similar observations in both FBG and HbA1c suggested an improving effect of PNPLA3 rs101002 on glucose homeostasis, especially in chronic hepatitis B patients with hepatic steatosis." (PMID 28695131, 2017). "Previous studies have reported a consistent association of PNPLA3 rs738409 and TM6SF2 rs58542926 with hepatic steatosis, which results in increased future health care expenditures." (PMID 26847197, 2016). "Associations of the single nucleotide polymorphisms (SNP) PNPLA3 rs738409 and TM6SF2 rs58542926 with hepatic steatosis have recently been established." (PMID 26847197, 2016). "To date, the PNPLA3 I148M and TM6SF2 E167K gene variants are the major determinants of interindividual differences in liver steatosis and susceptibility to progressive NASH." (PMID 26273621, 2015). "The impact of the PNPLA3 rs738409 genotype on fatty liver varied among patients with different BMIs." (PMID 26139292, 2015). "Recent publications showed a significantly higher risk for hepatic steatosis, more pronounced necroinflammation and an accelerated fibrosis progression rate in HCV monoinfected patients harbouring the PNPLA3 risk allele G." (PMID 26599080, 2015). "In recent years, the patatinlike phospholipase domain-containing 3 (PNPLA3) gene has been studied in relation to liver steatosis and liver disease outcomes." (PMID 25290313, 2014). "A single nucleotide polymorphism (SNP) of patatin-like phospholipase domain-containing 3 (PNPLA3) genes (rs738409) is associated with the severity of fibrosis and cirrhosis in patients with fatty liver disease." (PMID 25337145, 2014). "In chronic hepatitis C patients, several studies suggested that PNPLA3 genotype influences hepatic steatosis and liver fibrosis." (PMID 24349054, 2013). "This final list includes six genes associated with ALT elevation and/or hepatic steatosis (MAPK10, CPN1, TRIB1, PNPLA3, SAMM50 and MICAL3)." (PMID 23813869, 2013). "The PNPLA3 gene is responsible for the difference in prevalence of fatty liver disease between ethnic groups." (PMID 22978800, 2012). "We found significant associations of the PNPLA3 rs738409 G allele (92.3%) and GG genotype (69.2%) with cirrhosis among MASLD patients (p = 0.021 and p = 0.008, respectively), reinforcing the established role of PNPLA3 in hepatic steatosis and fibrosis progression." (PMID 40981175, 2025). "The PNPLA3 I148M variant, independent of its functional annotation with hydrolase activity and acyltransferase, results in hepatic steatosis, which can advance to fibrosis." (PMID 39394864, 2025).
Hepatic steatosis (continued). "For instance, five variants in or near TM6SF2, PNPLA3, HFE, APOE, and MTARC1 had comparably larger effects on HCC than on hepatic steatosis (p <0.05 by Cochran’s Q test), while HCC-associated variants in HSD17B13, KLF15, and TERT did not significantly associate with steatosis." (PMID 40823170, 2025). "The mutant 148 Isoleucine to Methionine (I148M) protein variant in the patatin-like phospholipase domain-containing 3 (PNPLA3) gene results in a loss of function of the protein determining triglyceride retention in the hepatocytes, thus resulting in hepatic steatosis." (PMID 39940335, 2025). "Hepatic steatosis in lean individuals can arise from non-metabolic mechanisms including genetic predisposition (PNPLA3, TM6SF2), gut microbiota dysbiosis, sarcopenia, and environmental influences such as diet and hormonal regulation." (PMID 41437157, 2025). "Noteworthy, the PNPLA3 rs738409 polymorphism has been found to be more common in individuals with hepatic steatosis, even in the absence of obesity and metabolic dysfunction." (PMID 40507673, 2025). "In this study, in the general population without fatty liver, the PNPLA3 rs738409 GG and CG genotypes were associated with increased liver fat mass over 4 years compared to the CC genotype." (PMID 40074353, 2025). "Even in individuals with the PNPLA3 rs738409 CC genotype, long-term exposure to aging, hyperglycemia, and dyslipidemia may lead to fatty liver development." (PMID 40074353, 2025). "To determine if LD targeting of hPNPLA3 I148M is required for the liver steatosis, we utilized PNPLA3-KO mice and re-expressed WT hPNPLA3, hPNPLA3 I148M, I148MAAEE, or GFP control specifically in the liver of mice and challenged them with a diet high in sucrose to induce liver steatosis." (PMID 39814233, 2025). "Among these noted genetic variants, evidence shows that the human PNPLA3 gene rs738409 C>G polymorphism (PNPLA3 rs738409/I148M) has a strong correlation to increased MASLD severity, including hepatic steatosis, fibrosis, cirrhosis, and hepatocellular carcinoma." (PMID 39324073, 2024). "However, despite significant research in in vitro and in vivo models, the mechanism by which PNPLA3 (I148M) induces hepatic steatosis is unclear." (PMID 38674929, 2024). "Unexpectedly, most of the previously recognized NAFLD-associated genes, including PNPLA3, were not simply related to fatty liver in the present study." (PMID 37304843, 2023). "This is in accordance with a recent study that demonstrated that silencing of PNPLA3 could effectively attenuate hepatic steatosis as well as reduce liver fibrosis via lowering Timp2 expression levels." (PMID 36403577, 2023). "In obese individuals with hepatic steatosis, divided into 2 groups on the basis of PNPLA3 genotype, 6 d of a hypocaloric low carbohydrate diet (<20 g/d) led to a larger decrease in hepatic TG content (-45%) in individuals with the 148M mutation than in individuals without (-18%)." (PMID 37591342, 2023). "Recent studies carried out on an adult population with CD have demonstrated that PNPLA3 I148M gene variant is associated with the development and severity of hepatic steatosis, but not related to metabolic disorders." (PMID 36675276, 2023). "For example, this would allow an evaluation of the relationship between a traditional Mexican diet and hepatic steatosis among US-born individuals that are not carriers of the PNPLA3 risk allele." (PMID 38068856, 2023). "Birthplace (P-interaction = 0.02) and PNPLA3 risk allele carrier status (P-interaction = 0.04) modified the relationship between tMexS and hepatic steatosis but not fibrosis." (PMID 38068856, 2023). "However, an excess of n-6 PUFAs in the diet can serve as a substrate for the production of new triglycerides (TGs) and slow the hydrolytic function of PNPLA3, leading to liver steatosis." (PMID 36830856, 2023).
Hepatic steatosis (continued). "The study provided proof-of-concept in using an antisense oligonucleotide (ASO) against PNPLA3-I148M to ameliorate hepatic steatosis and NASH development and is currently in clinical trials (NCT04142424, NCT04483947) for patients who are homozygous for the variant." (PMID 36499091, 2022). "Our study shows that Greek children with hepatic steatosis had a significant percentage of the rs738409 polymorphism in the PNPLA3 gene, regardless of body weight." (PMID 36079710, 2022). "Moreover, both GCKR-P446L and PNPLA3-I148M variants have synergistic effects on the NAFLD risk, particularly on hepatic steatosis." (PMID 36672614, 2022). "In the present study, it was shown that although the induction of fatty liver caused a significant increase in PNPLA3 in the liver, NAFLD+LGG+HIIT do not show a significant increase compared to the healthy control group." (PMID 36110559, 2022). "Our study shows that frequencies of the rs738409 PNPLA3 variants were greater in both obese and nonobese pediatric patients of Greek origin with hepatic steatosis." (PMID 36079710, 2022). "Patients with liver steatosis (any grade) vs. nonsteatosis tended to harbor the PNPLA3 G allele variant [57.6% vs. 16.7% (p = 0.09)], but not TM6SF2 or MBOAT7-TMC4 variants." (PMID 36110512, 2022). "Therefore, the PNPLA3 I148M and TM6SF2 E167K gene variants are major determinants for interindividual differences in liver steatosis and susceptibility to NASH." (PMID 36612019, 2022). "This study shows that in Greekchildren, there is a significant association between the rs738409polymorphism in the PNPLA3 gene and hepatic steatosis, regardless of bodyweight." (PMID 36079710, 2022). "PNPLA3 p.I148M and TM6SF2 p.E167K were associated with increased hepatic steatosis in our cohort." (PMID 36555467, 2022). "In addition, PNPLA3 and TM6SF2 variants have been regarded as variants of interest for risk of liver steatosis even in transplant settings." (PMID 36028802, 2022). "Evidence suggests that a single nucleotide polymorphism (SNP) in the PNPLA3 gene, rs738409, increases the risk and progression of NAFLD and may modify the relationship between certain dietary factors and liver steatosis." (PMID 34280991, 2021). "In this evaluation of an admixed HCV population, neither TM6SF2 nor PNPLA3 polymorphisms were independently associated with hepatic steatosis or fibrosis." (PMID 33622266, 2021). "PNPLA3 I148M induces hepatic steatosis by retaining polyunsaturated triglycerides, and increasing lipogenesis, and in children, evidence suggests that it may be a stronger predictor than IR and BMI." (PMID 33102800, 2020). "PNPLA3 rs738409 has been observed to confer predisposition to hepatic steatosis in obese youth without increasing the level of insulin resistance." (PMID 32561908, 2020). "A recent study showed that silencing Pnpla3 with antisense oligonucleotides improved liver steatosis and fibrosis in Pnpla3 I148M knock-in mice, indicating that PNPAL3 could be a potential target for treatment in human." (PMID 33363067, 2020). "Although the mechanism by which PNPLA3 leads to hepatic steatosis accumulation remains unknown, it was shown to play a role in hepatocellular lipid droplet remodeling and very low-density lipoprotein secretion." (PMID 32685690, 2020). "Very recently, it has been highlighted that inhibition of the mutant Pnpla3 may be used as a therapeutic target to treat fatty liver disease." (PMID 32443539, 2020). "Therefore, PNPLA3 rs738409 C > G variant carriers, with a shift of DAG distribution and composition, would present seemingly paradoxical severe liver steatosis and conserved insulin sensitivity." (PMID 31447675, 2019). "Interestingly, human PNPLA3(148M) transgenic mice develop hepatic steatosis on chow or high-sucrose diet." (PMID 31921875, 2019). "This activity serves to remodel the lipids in hepatic LD but does not explain the hepatic steatosis associated with PNPLA3(148M)." (PMID 29555681, 2018).
Hepatic steatosis (continued). "Since DAG (FA18:1) has been implicated in hepatic insulin resistance, the unaltered proportion of DAG (FA18:1) in I148M PNPLA3 carriers with fatty liver may explain the normal insulin sensitivity in these subjects." (PMID 30227635, 2018). "Sequence variations in patatin like phospholipase domain containing 3 (PNPLA3) might lead to hepatic steatosis and liver injury." (PMID 30513925, 2018). "PNPLA3 CG and GG carriers with CD have a higher susceptibility to hepatic steatosis, but not to metabolic syndrome." (PMID 30189691, 2018). "While PNPLA3 and TM6SF2 appear to be the most prominent population-wide determinants of hepatic steatosis, other relatively rare or less prominent genetic defects in intrahepatic lipid metabolism have been shown to cause fatty liver." (PMID 30355853, 2018). "The negative correlation may indicate a regulatory function of APOC1P1. rs1883350 is associated with fatty liver disease and we identified one liver edQTL slightly downstream of PNPLA3 (Patatin-like phospholipase domain-containing protein 3)." (PMID 29527417, 2018). "We, therefore, investigated the PNPLA3 polymorphisms by deep sequencing in biopsy-proven chronic hepatitis B patients, with or without hepatic steatosis, from Southern, Central, and Northern China." (PMID 28695131, 2017). "The interaction between PNPLA3 SNPs and hepatic steatosis was determined by liver pathology." (PMID 28695131, 2017). "A recent study demonstrated that the rs2294918 variant of the PNPLA3 gene is also significantly associated with hepatic steatosis in an Italian population, independent of rs738409." (PMID 27532011, 2016). "It is suggested that the genetic background of the predisposition of NAFLD could be strong, and the patatin like phospholipase containing domain 3 gene (PNPLA3) is regarded as one of the most crucial genes in the development of hepatic steatosis." (PMID 27905898, 2016). "Unexpectedly, increased hepatic steatosis is actually associated with lower HBV DNA levels, but this finding may be explained by the association of PNPLA3 polymorphisms with both steatosis and lower HBV DNA levels." (PMID 28883965, 2016). "Second, our data demonstrated that variability in PNPLA3 transcription alone does not contribute to the risk of fatty liver or disease severity." (PMID 27744419, 2016). "The proportions of PNPLA3 rs738409 GG genotype carriage were 7.8% (44/563), 15.8% (58/367) and 19.3% (17/88) in patients with no (liver fat content <5%), mild (5–33%) and moderate/severe (>66%) hepatic steatosis, respectively (trend P < 0.001)." (PMID 26139292, 2015). "We aimed to assess the impact of PNPLA3 SNP (rs738409) on (i) fibrosis progression rate and development of advanced fibrosis, (ii) liver steatosis, (iii) portal hypertension, and (iv) virological response to PEGIFN/RBV therapy in a large cohort of HIV/HCV coinfected patients." (PMID 26599080, 2015). "In addition, this is also the first study to investigate the influence of the PNPLA3 on development of hepatic steatosis and portal hypertension in a large cohort of the special population of HIV/HCV coinfected patients." (PMID 26599080, 2015). "In our cohort we did not detect any significant association between the PNPLA3 variant and the presence of fatty liver." (PMID 26346943, 2015). "In summary, the PNPLA3 (rs738409) SNP is neither associated with faster liver fibrosis progression, nor with advanced fibrosis nor significant hepatic steatosis in HIV/HCV coinfection." (PMID 26599080, 2015). "Further, mice over-expressing the PNPLA3 148Met developed liver steatosis on high sucrose diet, which suggests that the PNPLA3 148Met may be involved in the hepatic de novo lipogenesis." (PMID 24563329, 2014). "Alternatively, older age may synergize with PNPLA3 I148M in determining hepatic steatosis, which would favor viral replication during the acute infection, thus setting the stage for faster disease progression." (PMID 25171251, 2014).
Hepatic steatosis (continued). "Recent reports have suggested that PNPLA3, IL28B and TLR4-associated single nucleotide polymorphisms (SNPs) may have an impact on hepatic steatosis or fibrosis in patients with chronic HCV infection." (PMID 24349054, 2013). "Recently its function has been elucidated to be LPAAT activity, mediating one of the steps in the TG synthesis pathway but loss of Pnpla3 in mice did not cause fatty liver." (PMID 23977068, 2013). "The PNPLA3 genotype interacts with both nonmodifiable (age, sex, genetic ancestry) and modifiable risk factors (visceral adiposity, obesity, insulin resistance, lipids) to multiplicatively increase risk of hepatic steatosis." (PMID 40166930, 2025). "Taken together, these results could suggest that the increase of VLDL synthesis due to hepatic fat accumulation in PNPLA3 I148M might be counteracted by the PUFA‐PC deficiency leading to no net difference in VLDL secretion in I148M fatty liver patients." (PMID 39394864, 2025). "Though International literature documented the risk of PNPLA3 rs738409 as the predictors for MAFLD but the present study for the first time proved the role of PNPLA3 rs 738408 in MAFLD and its association with progression of fatty liver disease and documenting this relation in Pakistan." (PMID 40469136, 2025). "However, this does not explain the fact that deletion of PNPLA3 in mice does not cause hepatic steatosis and that expression of PNPLA3 I148M is sufficient to promote TAG accumulation." (PMID 38247511, 2024). "Another study comparing the effect of a dietary intervention between subjects with PNPLA3 GG genotype and wildtype ones has demonstrated that mutated patients exhibited a greater weight loss and, as a consequence, a greater reduction in liver steatosis compared to not mutated ones." (PMID 35276911, 2022). "Thirdly, we did not investigate the genetic variations linked to hepatic steatosis, such as patatin-like phospholipase domain-containing protein 3 (PNPLA3), which may shed more light on the pathophysiology of IBD-related NAFLD." (PMID 36233826, 2022). "Our null findings imply that the benefits and/or deleterious effects of dietary intake on levels of hepatic steatosis may be the same for MO adults regardless of their level of genetic risk associated with PNPLA3 genotype status." (PMID 34280991, 2021). "Recently, a gene polymorphism in the PNPLA3 (patatin-like phospholipase) coding domain (rs738409) has been identified as a key predictor of liver disease progression from fatty liver to steatohepatitis, in the setting of both alcoholic and non-alcoholic liver disease." (PMID 33800964, 2021). "Additionally, prevalence of hepatic steatosis declined in PNPLA3 rs738409 G-allele carriers (47.3 vs. 41.8%) and non-carriers (57.8 vs. 47.8%)." (PMID 33917196, 2021). "Similarly, the introduction of the PNPLA3 (I148M) into mice genes resulted in hepatic steatosis." (PMID 33926085, 2021). "Pnpla3 specifically catalyzes coenzyme A-dependent acylation of 1-acyl-sn-glycerol 3-phosphate (2-lysophosphatidic acid/LPA) to generate phosphatidic acid, an important metabolic intermediate and precursor of both TGs and glycerophospholipids, and is associated with fatty liver disease." (PMID 34167568, 2021). "The PNPLA3 I148M variant causes impaired triglyceride mobilization and accumulation of lipid droplet by evading ubiquitylation and by comparative gene identification–58 (CGI–58)–dependent inhibition of adipose triglyceride lipase, resulting in hepatic steatosis." (PMID 33256232, 2020). "This hypothesis proved to be incompatible with the subsequent finding that genetic deficiency of PNPLA3 in mice fails to result in hepatic steatosis." (PMID 29555681, 2018). "Thus, the hepatic steatosis associated with PNPLA3(148M) does not appear to reflect a loss in the lipid remodeling activity of the enzyme." (PMID 29555681, 2018).